DISP1 (dispatched RND transporter family member 1)
Description:
Functions in hedgehog (Hh) signaling. Regulates the release and extracellular accumulation of cholesterol-modified hedgehog proteins and is hence required for effective production of the Hh signal (By similarity). Synergizes with SCUBE2 to cause an increase in SHH secretion.
Synonyms: DISPA; MGC13130; DKFZP434I0428; MGC16796; HPE10
Tractability: Small molecule: a structure with a bound ligand is known. Antibody: UniProt predicts a signal peptide or a membrane-spanning region; the Human Protein Atlas places it where antibodies can reach. PROTAC: ubiquitination databases record sites on it.
Gene: Protein-coding gene on chromosome 1 (222,814,730 to 223,006,258, forward strand). Ensembl gene ENSG00000154309.
Subcellular location: Membrane
Subcellular location (Human Protein Atlas): Plasma membrane
Gene Ontology:
Molecular function: protein binding; molecular carrier activity
Biological process: diaphragm development; peptide transport; regulation of protein secretion; smoothened signaling pathway
Cellular component: basolateral plasma membrane; membrane
Genetic constraint (gnomAD): Loss-of-function variants: 27 observed, 36.2 expected, observed/expected ratio (o/e) 0.75, 90% interval 0.55 to 1.03. The upper end of that interval is the gene's LOEUF score, 1.03, which puts it in group 4 of 6, group 1 being the genes least tolerant of losing a copy. Missense variants: 1,596 observed, 1,972.2 expected, observed/expected ratio (o/e) 0.81, 90% interval 0.78 to 0.84. Synonymous variants: 634 observed, 727.59 expected, observed/expected ratio (o/e) 0.87, 90% interval 0.82 to 0.93.
Gene-disease validity (ClinGen):
ClinGen rates the evidence that DISP1 causes each of these diseases.
holoprosencephaly (autosomal dominant): Limited. Holoprosencephaly (HPE) is a complex brain malformation resulting from incomplete cleavage of the prosencephalon, occurring between the 18th and 28th day of gestation, and affecting both the forebrain and face, which results in neurological manifestations and facial anomalies of variable severity.
Homologues: Orthologues: chimpanzee DISP1 (99% identical), macaque DISP1 (97% identical), rabbit DISP1 (90% identical), pig DISP1 (87% identical), mouse Disp1 (84% identical), rat Disp1 (82% identical), guinea pig DISP1 (77% identical), dog DISP1 (74% identical), zebrafish disp1 (61% identical), Drosophila melanogaster disp (25% identical), Caenorhabditis elegans ptd-2 (14% identical), Drosophila melanogaster ptc (9% identical), and 3 more. Paralogues in human: DISP2 (32% identical), SCAP (13% identical), NPC1L1 (12% identical), PTCH1 (11% identical), NPC1 (11% identical), PTCH2 (10% identical), PTCHD3 (9% identical), DISP3 (9% identical), PTCHD1 (8% identical), PTCHD4 (7% identical).
Diseases named in the same sentence as DISP1 in open-access papers:
DISP1 is named in the same sentence as 7 diseases in open-access papers, as found by Europe PMC text mining. Sharing a sentence is not in itself a finding about the gene and the disease. The quoted sentences say what the papers report.
cleft palate (3 papers, 2009 to 2017). Cleft palate is a fissure type embryopathy that affects the soft and hard palate to varying degrees. "Except for DISP1, all these genes have been associated with cleft palate in mouse models, whereas only LHX8 and GAD1 have been associated with cleft palate disorders in humans." (PMID 19557186, 2009). "The normality of DISP1 and Shh seems to be the major reason for the absence of a cleft palate and CHD in our patient." (PMID 28286461, 2017).
Coffin-Siris syndrome (1 paper, 2021). Coffin-Siris syndrome (CSS) is a rare congenital multi-systemic genetic disorder characterized by aplasia or hypoplasia of the distal phalanx or nail of the fifth digit, developmental delay, intellectual disability, coarse facial features, and other variable clinical manifestations. "Mutations were detected in four of them: one with a mutation in the ARID1B gene (Coffin–Siris syndrome), one with a microdeletion (Xq28), one with a non‐relevant heterozygous mutation in the DISP1 gene and one with a DCC mutation." (PMID 32484578, 2021).
diabetes mellitus (1 paper, 2023). A metabolic disorder characterized by abnormally high blood sugar levels due to diminished production of insulin or insulin resistance/desensitization. "These included proteins expressed by pancreatic islet cells (Ptch1, Disp1, Pck1, and Cacna1e) as well as proteins known to be associated with diabetes mellitus susceptibility or glucose metabolism (Adcy8, Perm1, Sorbs1, and Pla2g6)." (PMID 37934865, 2023).
pancreatic cancer (1 paper, 2025). "Among the previously known and here confirmed interactors (CDH1, DISP1, SCFD1, USE1, TSG101, and USP8), CDH1 (E‐cadherin), a critical adhesion molecule, is frequently lost or downregulated in pancreatic cancer, promoting epithelial‐to‐mesenchymal transition (EMT) and enhancing tumor invasiveness." (PMID 40952239, 2025).
tumor (3 papers, 2012 to 2025). "All 10 DEGs found in the patients who lived in Sao Paulo city compared to the MRSP were associated with cell proliferation and tumor development (BMP4, CTNNBP1, DISP1, DVL1, ERBB4, PRLR, WNT5b, LEF1, PGR, and PTEN)." (PMID 36768749, 2023).
DISP1 also shares sentences with these, for which no sentence is quoted: developmental delay (1 paper); Oligodontia (1).